TNF (tumor necrosis factor)
Diseases named in the same sentence as TNF in open-access papers (continued):
Sharing a sentence is not in itself a finding about the gene and the disease.
Arthritis (continued). "It was originally cloned from diploid human fibroblasts stimulated by TNF, and high levels of TSG-6 protein have been found in synovial fluids of patients with inflammatory joint disorders, as well as in the sera from bacterial sepsis and systemic lupus erythematosus patients." (PMID 31849677, 2019). "We have also reported that both GM-CSF-driven inflammatory pain and arthritis models (using exogenous GM-CSF), and GM-CSF-dependent inflammatory pain and arthritis models (e.g. zymosan-induced arthritis (ZIA)) are dependent on IRF4 and CCL17, and on TNF." (PMID 29622035, 2018). "In the current study we provide evidence that the GM-CSF→Jmjd3→IRF4→CCL17 pathway, originally identified in human and murine monocytes/macrophages, is required for CiOA pain and optimal arthritis development; however TNF is not involved." (PMID 29622035, 2018). "General overexpression of human TNF in mice phenocopies RA, whereas a stabilized TNF-α in mice (TNFΔARE) produces aggressive widespread (polyarticular) joint disease and Crohn’s like IBD, with arthritis occurring independently of T or B cells." (PMID 29556237, 2018). "IL-1 and TNF-α were required for arthritis induced by the transfer of anti-type II collagen antibodies (CAIA), while IL-6 was imperative for arthritis induced by the immunization with type II collagen (CIA), because IL-6 was essential for the differentiation of Th17 cells." (PMID 28753982, 2017). "Prophylactic TNF targeting resulted in delayed spondylitis and arthritis development and reduced arthritis severity, whereas therapeutic TNF blockade did not affect spondylitis and arthritis severity." (PMID 28824645, 2017). "Non-MHC genes that influence rat PIA arthritis severity include TNFα, IL-1β, IL-6, IL-17, and CCL-2, and joint damaging MMPs." (PMID 29145473, 2017). "TNF-α levels correlated with the arthritis score but not with ankle diameter (r = 0.22, p = 0.25, not shown)." (PMID 28759646, 2017). "One of the best-known mRNA substrates for TTP is TNFα: Mice lacking TTP have high levels of TNFα due to low mRNA turnover, leading to severe arthritis and cachexia." (PMID 27539829, 2017). "The role of TNFα in inflammatory hyperalgesia is fundamental; we detected abundant expression of TNFα mRNA in the inflamed synovium of both TRPC5 WT and KO mice, 14 days following CFA-induced arthritis." (PMID 27165180, 2017). "In addition, compared with arthritis control, PDCD5 tg mice reduced serum levels of the pro-inflammatory cytokines IFN-γ, IL-6, IL-17A and TNF-α and upregulated the expression of the anti-inflammatory cytokine IL-4." (PMID 29228993, 2017). "In summary, arthritis improvement when targeting TNF-α does not result in a constant and uniform alteration of the host defense against infection." (PMID 29184553, 2017). "The results show that WJHL can significantly alleviate the progression of CIA, reduce ankle swelling, arthritis score, pathological changes, and bone destruction, and increase the level of OPG by inhibiting the levels of TNF-α, IL-1β, IL-6, and IL-17 in the serum of CIA mice." (PMID 28562338, 2017). "A role of pro-inflammatory cytokines can be discarded because TNF-α and IL-1β levels are not elevated at this time of arthritis." (PMID 26761790, 2016). "The effector phase of arthritis involves several molecular mediators including TNF and IL-1, but not IL-617." (PMID 27995997, 2016). "Mice lacking capacity to produce TNF-α have higher mortality and inefficient bacterial clearance in S. aureus arthritis and brain abscess model." (PMID 27446000, 2016). "Our data demonstrate that anti-TNF antibody treatment alone modulates arthritis severity by favoring increase in Treg but not collagen-specific Treg or APC reprogramming with pro-regulatory properties." (PMID 27516061, 2016). "None of the mice that overexpress TNF-α only in the lung had any arthritis by histology similar to wild-type controls." (PMID 27450561, 2016).
Arthritis (continued). "With regards to pro-inflammatory cytokines, IL-1β correlates with and partially precedes the course of clinical arthritis, whereas serum IL-6 and TNFα are not changed during PIA." (PMID 27227821, 2016). "During the first 24 h following TNF neutralization, no apparent changes to clinic analog parameters or histopathologic signs of arthritis were observed." (PMID 26477946, 2015). "TNFα influences the pathogenesis of some of the clinical manifestations (e.g., anemia, arthritis), whereas others are independent of both TNFα and IFN-I (e.g., DAH)." (PMID 26097482, 2015). "Immunosuppression of the mice with anti-TNF-alpha treatment (once a week during weeks 7 to 10) did not have any effect on the culture results or on the arthritis development (groups 11 and 12)." (PMID 25816291, 2015). "Thus, ADAMTS-7 expression was elevated during disease progression in surgically induced OA and collagen-induced arthritis model, and the increasing ADAMTS-7 upregulated the level of inflammatory cytokines including TNF-α." (PMID 26696755, 2015). "IL-6, as well as TNF, IL-1β and PGE2, were reported to up-regulate the RANKL (receptor activator of NF-κB ligand) expression, which was an important prerequisite for osteoclast differentiation and arthritis." (PMID 25602164, 2015). "The orally available PDE4 inhibitor inhibits spontaneous TNF-α production from human synovial membrane cultures and reduces the severity of disease in murine models of arthritis with similar efficacy to rolipram, but without any significant adverse effects." (PMID 26370839, 2015). "Likewise, the intra-articular injection of mBSA that triggers arthritis in AIA, is accompanied by a strong recall response of proinflammatory cytokines in serum, including IL-6, IL-10, IL-12, and TNF." (PMID 26512984, 2015). "In human arthritis, areas with inflammation were shown to be predictive of bone formation, but bone formation does not seem to be blocked by anti-tumor necrosis factor alpha (TNFα) treatment." (PMID 25889670, 2015). "Blockade of TNF with etanercept stopped, without improving, disease progression in mice with mild, moderate and severe arthritis, resulting in an average clinical score 25 % lower than vehicle-treated mice, but 39 % higher than dual treatment." (PMID 26653844, 2015). "OPN-deficient mice exhibit reduced disease in arthritis models not by altering TNF-α levels but by suppressing angiogenesis in the joints, and angiogenesis is enhanced by IL-6 signaling instead of by TNF-α." (PMID 26698858, 2015). "Addressing the breach of tolerance, the antibody mediated effector phase and here the TNF driven cytokine/stromal interaction in joint inflammation and destruction, no arthritis model shows a potential effect by IL-36 signaling with an impact on the disease." (PMID 25111378, 2014). "FAK inhibitors reduce synovial fibroblast invasion and migration, but synovial fibroblast migration and TNFα-induced arthritis do not rely on FAK itself." (PMID 25280866, 2014). "Although the study without LPS indicated that LPS was not necessary for induction of arthritis, it did appear to improve synchronization and severity of the disease and open up a good window for TNFα inhibitor studies." (PMID 25344414, 2014). "Because murine arthritic synovial fibroblasts had impaired invasion upon FAK depletion, we sought to determine if TNFα-induced arthritis would be lessened in the absence of FAK." (PMID 25280866, 2014). "Indeed in our previous publications, we have shown that BC-associated metastasis is significantly augmented in mice with arthritis and that IL-17A, IL-6, COX-2, VEGF, MMP-9, IGF-II, M-CSF and TNF-α are all major players." (PMID 24674692, 2014). "Loss of FAK reduced invasion in murine arthritic synovial fibroblasts, but not migration or TNFα-induced arthritis severity and joint erosions." (PMID 25280866, 2014).
Arthritis (continued). "In this study, we show that FAK inhibitors reduce rheumatoid synovial fibroblast invasion and migration, but that FAK itself is required only for synovial fibroblast invasion, not migration or murine TNFα-induced arthritis." (PMID 25280866, 2014). "It has been reported that IL-17A is strongly dependent on TNF-α in the early stages of experimental arthritis, and could induce the production of TNF-α at later stages of experimental arthritis." (PMID 24788826, 2014). "Also, green tea polyphenols added to drinking water reduce the incidence of collagen-induced arthritis and decrease the levels of COX-2 and tumor necrosis factor (TNF)-α in articular joints in mice." (PMID 25516005, 2014). "In the present retrospective study, we primarily wanted to verify the proportion of patients with PsA in whom there were no clinical or CEUS signs of joint inflammation after 12 months of effective anti-TNF therapy." (PMID 24653837, 2014). "The present study was designed to identify antiarthritic effects of NHAG in adjuvant-induced arthritis (AIA) and its effects on the circulatory levels of proinflammatory cytokines IL-1β and TNF-α and oxidative stress markers glutathione, nitric oxide, and peroxide." (PMID 23971039, 2013). "Considering the great importance of TNFα for the induction and progression of arthritis, it is not surprising that several mouse models overexpressing the TNFα cytokine have been established." (PMID 23740547, 2013). "Although the etiology of the spontaneous arthritis has not yet been fully elucidated, it is known that disease is dependent on TNFα and IL-17." (PMID 23840826, 2013). "The described products may represent useful research tools for the study of the anti-arthritic properties of TNF blockade and of IL10-based immunocytokines in syngeneic immunocompetent models of arthritis." (PMID 24289726, 2013). "In our previous study using CIA, Kampo medicine decreased the serum IL-6 levels, but not TNF-α, suggesting that the suppression of Th17 cell activation by Kampo therapy probably improved the development of arthritis." (PMID 22577464, 2012). "Mun and co-workers showed that curcumin suppressed TNF-α-induced JNK activation in human fibroblast-like synoviocytes (FLSs) and SW1353 (a human chondrosarcoma cell line) cells leading to an amelioration of collagen-induced arthritis." (PMID 23152905, 2012). "TNF-α and IL-6 mRNA expressions in whole hind limbs were up-regulated in immunized mice with arthritis compared with intact mice, and MTX treatment did not reduce TNF-α or IL-6 mRNA expressions." (PMID 22546471, 2012). "We have also reported that Kampo therapy resulted in a decrease in serum IL-6 levels, but not TNF-α levels, as well as the suppression of arthritis development, based on the observations of the CIA mouse model." (PMID 22577464, 2012). "Taking into account that this adipokine has been shown to be downregulated by cytokines such as TNF and IL6, arthritis-induced decrease in adiponectin may be due to the inflammatory mediators." (PMID 23781298, 2012). "GPI-induced arthritis is considered to be a closer model of human RA than CIA with regard to its dependency on CD4+ T cells and response to biological agents, such as anti-TNF-α and anti-IL-6 receptor antibody." (PMID 23251456, 2012). "GPI-induced arthritis is a newer and closer model of human RA with regard to its dependency on CD4+ T cells and reactivity to biological treatments such as blockade of IL-6 and TNF-α, which are well known to be effective in human RA." (PMID 23251456, 2012). "As TNFα-converting enzyme is thought to be activated in rats developing arthritis, especially in the early stage of the disease, the low joint TNFα levels are unlikely to reflect a defective processing of its mRNA." (PMID 22414623, 2012). "The results indicated that the beneficial antigouty arthritis effect of EMI may be mediated, at least in part, by inhibiting TNF-α and IL-1β expression in the synovial tissues." (PMID 23304232, 2012).
Arthritis (continued). "Furthermore, mice transgenic for TNF-α, and mice with disregulated TNF-α production develop arthritis." (PMID 22085488, 2011). "As a result, the activation of endogenous or exogenous mesenchymal cells by TNF-α will not take place, resulting in the inhibition of arthritis development." (PMID 21151872, 2010). "Our in vitro study indicated that stimulation by TNFα up-regulated HDAC activity in RASFs, suggesting the downstream role of HDAC in exacerbation of the inflammation, and that the inhibition of HDAC activity results in the suppression of arthritis." (PMID 20609223, 2010). "The proinflammatory cytokine tumor necrosis factor alpha (TNF-α) is not only critical for host defense against microbial agents but also plays an important role in joint inflammation and cartilage destruction in various forms of arthritis." (PMID 20691044, 2010). "The results of this study of patients with AS categorized by enthesitis and arthritis are consistent with previous predictor analyses, which found that enthesitis and arthritis did not influence the effect of TNF-antagonist therapy." (PMID 20230622, 2010). "Noassociation was found between TNF-α levelsand EN/PPE and arthritis." (PMID 19197380, 2008). "We demonstrated that both TZDs reduced the expression of IL-1β and TNF-α in arthritic synovium, a finding consistent with a recent report of their decrease by the PPAR-γ agonist THR0921 in joints of mice with established collagen-induced arthritis." (PMID 18199331, 2008). "A single injection of anti-TNF-α and anti-IL-6 mAbs and two injections of CTLA-4Ig reduced the severity of arthritis in mice, whereas injections of anti-IFN-γ and anti-IL-12 mAbs tended to exacerbate arthritis." (PMID 18534002, 2008). "These and other studies led to the hypothesis that TNF-α was a therapeutic candidate in RA, and the demonstration that TNF-α blockade in murine arthritis ameliorated disease led to the testing of anti-TNF biologicals in humans." (PMID 18353171, 2008). "In addition, at the time point of arthritis onset, a substantial number of the infiltrating inflammatory cells expressed HMGB1 in their cytoplasm, apparently more than cells expressing TNF or IL-1β." (PMID 17397533, 2007). "Because TNF-α levels are elevated in arthritis and TNFR55 expression is increased in arthritic disease, our future studies will determine whether TNF-α-mediated activation of neutral SMase and ceramide generation plays a role in cartilage degradation." (PMID 16696862, 2006). "Our data extend this knowledge: the selective inhibition of JNK1 is not effective to block inflammation in TNF-driven arthritis." (PMID 15642137, 2005). "Unlike IL-17A, TNF is considered more relevant to arthritis than skin inflammation." (PMID 41583484, 2025). "In this model, E. lenta exacerbated arthritis severity by enhancing the immune response to type II collagen, which led to increased levels of pro-inflammatory cytokines in the serum, including interleukin (IL)-9, IL-17, IL-23, interferon (IFN)-γ and tumor necrosis factor (TNF)-α." (PMID 41431641, 2025). "Conversely, microenvironmental stimuli like oxidative stress and TNF-α activate CASP3 through mitochondrial or death receptor pathways, rapidly inducing apoptosis in chondrocytes, osteoblasts, and osteocytes, thereby driving bone-destructive processes such as OP or arthritis." (PMID 41303381, 2025). "Additionally, within 10 days after arthritis onset, apremilast significantly inhibits spontaneous release of TNF-α, and reduces the severity of arthritis in mice without apparent side effects." (PMID 38915460, 2024). "TNF blockade may be used in arthritis-predominant AOSD patients without systemic symptoms and upon suboptimal response to both IL-1 and IL-6 blockade." (PMID 37669122, 2024).
Arthritis (continued). "In conclusion, our data demonstrate that in two genetic mouse models of arthritis, driven by either TNF or IL‐1β, musculoskeletal disease develops independent of the microbiota, independent of gut inflammation, but instead is driven by joint‐specific sterile factors." (PMID 37694693, 2023). "Pre-arthritis treatment was also effective for methotrexate, but not for anti-TNF and anti-IL1." (PMID 36796580, 2023). "Here, we show that in arthritis pain, dorsal horn microglia acquire a unique transcriptional profile that is driven by TLR4 upregulation and is enriched in pathways regulating the production and effect of IL-1β, TNF-α and IFN-β, which have been reported to regulate nociception in the K/BxN ST model." (PMID 37349313, 2023). "Additionally, CBD’s effects were enhanced by adding TNFα, suggesting that CBD preferably acts in a pro-inflammatory environment and that CBD might ameliorate arthritis by targeting pro-inflammatory synovial fibroblasts." (PMID 37917863, 2023). "Furthermore, as the proinflammatory cytokines such as IL-1 and TNF-alpha are not highly expressed in the tissue, this suggested that the tissue was not undergoing a full-blown inflammatory reaction such as that of arthritis." (PMID 37509659, 2023). "The downregulation of SPARC synthesis by inflammatory cytokines, including IL-1 and TNF-α, during the acute phase of arthritis, as verified by Nakamura, further supports our hypothesis about the role of SPARC in immune function and suggests that TNF-α can modulate SPARC reversal." (PMID 37355563, 2023). "During the development of OA, proinflammatory cytokines such as interleukin-1ß (IL-1β) and tumor necrosis factor-α (TNF-α) are increased in cartilage and serve as critical mediators that impair the balance between excessive cartilage damage and the cartilage repair process in arthritis." (PMID 35488351, 2022). "The previous investigation revealed that insulin-like growth factor 1 (IGF-1) could upregulate the synthesis of ChS-rich aggregating proteoglycans even at the relatively high concentration of inflammatory factors such as IL-1 and TNF-α, indicating that IGF-1 has the potential to ease arthritis." (PMID 36032667, 2022). "In our study, the lack of association between the arthritis and the αSMA+ PLV-LMCs may be due to differential rates of tissue recovery with TNF inhibition, while these factors could be related at earlier stages of disease." (PMID 35882971, 2022). "One study reported that TNF-α levels in synovial membranes of AOSD patients show a significantly increase compared to healthy controls, suggesting that the overexpression of TNF-α might lead to arthritis." (PMID 36072947, 2022). "Furthermore, our data indicated that a high frequency of TNF-α-secreting T cells contributed to the pathogenesis of ICI-related arthritis and pneumonitis as anti-TNF-α treatment significantly ameliorated the severity of ICI-related arthritis and pneumonitis." (PMID 36016934, 2022). "Lymph node cells were isolated from model rats and administered with DAPs, and it was found that the expression levels of IL-1β, IL-2, IL-6, TNF-α and IFN-γ were significantly reduced, while the acceleration of arthritis severity could be attributed to the elevation of these factors." (PMID 36235835, 2022). "Amygdalin may reduce TNF-, SIAM-1, and TNF- in rats with type II collagen-induced arthritis." (PMID 36291723, 2022). "Iguratimod is a new antirheumatic drug that suppresses the production of tumor necrosis factor α (TNFα), interleukin 6 (IL-6), and IL-8 in lipopolysaccharide-stimulated THP-1 cells, and inhibits cartilage and bone damage in DBA/1J mice with type II collagen (COL-II)-induced arthritis." (PMID 35387545, 2022). "On the other hand, TNF-α has a positive correlation with the number of DCX+ and Ki67+ cells in the dentate gyrus in females, which may indicate a faster recovery of adult neurogenesis but at the same time, may worsen the clinical course of arthritis." (PMID 34830044, 2021).